YARS1 (tyrosyl-tRNA synthetase 1)
Description:
Tyrosine--tRNA ligase that catalyzes the attachment of tyrosine to tRNA(Tyr) in a two-step reaction: tyrosine is first activated by ATP to form Tyr-AMP and then transferred to the acceptor end of tRNA(Tyr) (Probable). Also acts as a positive regulator of poly-ADP-ribosylation in the nucleus, independently of its tyrosine--tRNA ligase activity. Activity is switched upon resveratrol-binding: resveratrol strongly inhibits the tyrosine--tRNA ligase activity and promotes relocalization to the nucleus, where YARS1 specifically stimulates the poly-ADP-ribosyltransferase activity of PARP1.
Synonyms: TyrRS; YARS; YTS; YRS; CMTDIC; IMNEPD2
Tractability: Small molecule: a structure with a bound ligand is known; it has a high-quality binding pocket; it belongs to a druggable protein family. PROTAC: ubiquitination databases record sites on it; a small molecule that binds it is known.
Target class: Enzyme; Ligase
Gene: Protein-coding gene on chromosome 1 (32,775,237 to 32,818,031, reverse strand). Ensembl gene ENSG00000134684.
Subcellular location: Cytoplasm; Nucleus
Subcellular location (Human Protein Atlas): Cytosol; Nuclear bodies
Pathways (Reactome):
Metabolism of proteins: Cytosolic tRNA aminoacylation
Gene Ontology:
Molecular function: protein binding; RNA binding; small molecule binding; tyrosine-tRNA ligase activity; interleukin-8 receptor binding; aminoacyl-tRNA ligase activity; ATP binding; nucleotide binding; tRNA binding
Biological process: response to starvation; tyrosyl-tRNA aminoacylation; apoptotic process; response to stress; tRNA aminoacylation for protein translation
Cellular component: cytoplasm; cytosol; nuclear body; nucleus; extracellular region
Genetic constraint (gnomAD): Loss-of-function variants: 35 observed, 63.24 expected, observed/expected ratio (o/e) 0.55, 90% interval 0.42 to 0.73. The upper end of that interval is the gene's LOEUF score, 0.73, which puts it in group 3 of 6, group 1 being the genes least tolerant of losing a copy. Missense variants: 523 observed, 673.61 expected, observed/expected ratio (o/e) 0.78, 90% interval 0.72 to 0.83. Synonymous variants: 234 observed, 260.34 expected, observed/expected ratio (o/e) 0.9, 90% interval 0.81 to 1.
Gene-disease validity (ClinGen):
ClinGen rates the evidence that YARS1 causes each of these diseases.
Charcot-Marie-Tooth disease (autosomal dominant): Definitive. An inherited degenerative disorder involving the peripheral nerves.
Homologues: Orthologues: chimpanzee YARS1 (99% identical), macaque YARS1 (99% identical), mouse Yars1 (97% identical), rabbit YARS1 (96% identical), pig YARS1 (96% identical), dog YARS1 (96% identical), guinea pig YARS1 (95% identical), rat Yars1 (95% identical), zebrafish yars1 (82% identical), tropical clawed frog yars1 (79% identical), Drosophila melanogaster TyrRS (67% identical).
Diseases named in the same sentence as YARS1 in open-access papers:
YARS1 is named in the same sentence as 42 diseases in open-access papers, as found by Europe PMC text mining. Sharing a sentence is not in itself a finding about the gene and the disease. The quoted sentences say what the papers report.
gastric cancer (5 papers, 2020 to 2025). A primary or metastatic malignant neoplasm involving the stomach. "Previous studies on gastric cancer and hepatocellular carcinoma have provided evidence of YARS1's pro‐cancer effects." (PMID 38506098, 2024).
Charcot-Marie-Tooth disease (3 papers, 2023). "Thus far, autosomal dominant mutations in AARS1, GARS1, HARS1, MARS1, WARS1, SARS1 and YARS1 have been linked to peripheral neuropathies, predominantly Charcot-Marie-Tooth (CMT) disease." (PMID 37274211, 2023). "The most common condition, the Charcot-Marie-Tooth disease (CMT), is associated with dominant, monoallelic mutations in six aaRSs genes (e.g.,YARS1, MARS1, KARS1, WARS1, AARS1, GARS1, and HARS1)." (PMID 37495112, 2023).
neuroblastoma (3 papers, 2015 to 2023). Neuroblastoma (NB) is the most common solid, extracranial childhood tumor. "In the N2a neuroblastoma cells expressing YARS1 transgenes, we observed the typical "teardrop" distribution of the synthetase that was perturbed when expressing the YARS1CMT mutation." (PMID 38003325, 2023). "Biochemical studies uncover yet unknown actin-bundling property of YARS1 to be enhanced by a CMT mutation, leading to actin disorganization in the Drosophila nervous system, human SH-SY5Y neuroblastoma cells, and patient-derived fibroblasts." (PMID 36890170, 2023).
Alzheimer disease (2 papers, 2023 to 2025). A progressive, neurodegenerative disease characterized by loss of function and death of nerve cells in several areas of the brain leading to loss of cognitive function such as memory and language. "We previously showed that tyrosyl‐tRNA synthetase (TyrRS/YARS1) is reduced in Alzheimer's Disease (AD) brains, and tyrosine and phenylalanine decrease TyrRS in neurons." (PMID 40476370, 2025).
anemia (2 papers, 2021 to 2024). A reduction in the number of red blood cells, the amount of hemoglobin, and/or the volume of packed red blood cells. "Multiple biallelic mutations in TyrRS-encoding gene YARS1 lead to multisystem disorders exhibiting metabolic signatures like hypothyroidism, hypoglycemia, anemia, liver disease, and hearing impairments." (PMID 39260699, 2024). "LARS1- and MARS1-associated disorders are associated with neurological impairment, MRI abnormalities, liver disease, anemia, and endocrine abnormalities and show the greatest clinical overlap with the YARS1 p.(Arg367Trp)-associated phenotype delineated here." (PMID 34536092, 2021).
microcephaly (2 papers, 2021 to 2023). A congenital or acquired developmental disorder in which the circumference of the head is smaller than normal for the person's age and sex. "In 2019, in a large cohort of patients with microcephaly, the homozygous variant c.789C > A,p.(Phe263Leu) in YARS1 was associated with microcephaly, developmental delay and primordial dwarfism in one girl." (PMID 34536092, 2021).
bladder cancer (1 paper, 2024). "In conclusion, our analysis confirmed that the ceRNA network YARS1‐hsa‐miR‐148b‐3p/hsa‐miR‐191‐5p‐NFIA/EFEMP1/TRAK2/PAFAH1B1 is associated with bladder cancer prognosis." (PMID 38506098, 2024). "We investigated the regulatory associations between YARS1 and various aspects of bladder cancer, including senescence, ferroptosis and stemness." (PMID 38506098, 2024). "Gene enrichment analysis based on YARS1 revealed a strong association between YARS1 and DNA methylation in bladder cancer." (PMID 38506098, 2024). "According to our research, it has been discovered that the immune microenvironment of bladder cancer is significantly associated with YARS1, specifically the signalling pathways of the B cell receptor and T cell receptor." (PMID 38506098, 2024). "In summary, our results shed light on the increased expression of YARS1 in bladder cancer and its association with poor patient prognosis." (PMID 38506098, 2024). "In summary, this study establishes a robust association between YARS1 expression and immunotherapy in patients with bladder cancer." (PMID 38506098, 2024). "Initially, we presented the distribution of methylation probes associated with YARS1 on chromosomes in bladder cancer, followed by an analysis of the extensive genomic information linked to YARS1." (PMID 38506098, 2024). "In conclusion, our investigation substantiates the elevated expression of YARS1 in bladder carcinoma and the unfavourable prognosis associated with this elevated expression." (PMID 38506098, 2024). "Our results suggest that YARS1 plays an important role in bladder cancer and that the underlying mechanism may be accomplished by regulating the cell cycle, among other pathways." (PMID 38506098, 2024). "Therefore, it is plausible that the regulation of YARS1 in bladder cancer immunotherapy may also be associated with the behaviour of these two immune cells." (PMID 38506098, 2024). "Therefore, we propose that decreased methylation of YARS1 may be linked to its role in promoting bladder cancer progression." (PMID 38506098, 2024). "The expression of YARS1 in various grades of bladder cancer was examined using the TCGA‐BLCA data set." (PMID 38506098, 2024). "As expected, miRNAs were negatively correlated with their target genes, and hsa‐miR‐148b‐3p and hsa‐miR‐191‐5p were negatively correlated with YARS1 in bladder cancer." (PMID 38506098, 2024). "In conclusion, our detailed GSEA provides insights into the multiple potential functions of YARS1 in bladder cancer." (PMID 38506098, 2024). "We analysed the disparities in YARS1 protein expression between bladder cancer samples and normal bladder tissues using The Human Protein Atlas database." (PMID 38506098, 2024). "Our results demonstrated that YARS1 exhibited a substantial increase in expression in bladder cancer, particularly in high‐grade tumours, thereby implying its potential as an oncogene in bladder cancer." (PMID 38506098, 2024). "A Sankey plot demonstrates the distribution of bladder cancer samples with respect to high and low levels of YARS1 expression, considering variables, such as tumour size, stage, grade, tumour invasion, lymph node metastasis and patient survival status." (PMID 38506098, 2024). "Our findings revealed that the DNA methylation levels of YARS1 were significantly lower in bladder cancer samples than in normal bladder samples." (PMID 38506098, 2024). "Our findings suggest that the methylation levels of YARS1 are significantly lower in bladder cancer samples than in healthy bladder samples." (PMID 38506098, 2024). "In conclusion, our study suggests that YARS1 modulates ferroptosis, senescence and stemness in bladder cancer cells by interacting with MYC." (PMID 38506098, 2024). "To gain deeper insight into the role of YARS1 methylation in bladder cancer, we used the SMART database." (PMID 38506098, 2024).
bladder cancer (continued). "We analysed variations in YARS1 expression and survival in bladder cancer using multiple data sets, including TCGA‐BLCA, GSE13507 and bladder cancer‐specific tissue microarrays." (PMID 38506098, 2024). "Our findings revealed a significant increase in YARS1 expression in 19 paired bladder cancer cases compared to that in paired normal bladder tissues." (PMID 38506098, 2024). "We investigated YARS1 mRNA levels in normal bladder tissues and bladder cancer using two different data sets: TCGA‐BLCA and GSE13507." (PMID 38506098, 2024). "Considering that ferroptosis and cellular senescence can affect the stemness characteristics of tumour cells, we also examined the effect of YARS1 on bladder cancer stemness." (PMID 38506098, 2024). "The objective of this study was to explore the expression and prognostic relevance of YARS1 in bladder cancer using diverse bioinformatics methodologies and to analyse its biological functions." (PMID 38506098, 2024). "Our findings revealed a consistent elevation in the expression levels of YARS1 in bladder cancer samples compared to those in normal bladder tissues." (PMID 38506098, 2024). "This study aimed to explore the expression and prognostic significance of YARS1 in bladder cancer using The Cancer Genome Atlas (TCGA) BLCA and GSE13507 data sets." (PMID 38506098, 2024). "Our analysis unearthed a total of 10 methylation probes related to YARS1 that displayed substantial differences between bladder cancer and normal bladder samples." (PMID 38506098, 2024). "First, the correlation between YARS1 and immune cell infiltration in bladder cancer was explored using single‐cell analysis." (PMID 38506098, 2024). "To delve deeper into this relationship, we conducted a thorough investigation of variations in YARS1 DNA methylation levels in bladder cancer." (PMID 38506098, 2024). "Among these genes, MYC was found to interact with YARS1 in bladder cancer and to regulate cellular senescence and ferroptosis." (PMID 38506098, 2024). "To explore the biological role of YARS1, we performed gene enrichment analysis on samples from patients with bladder cancer." (PMID 38506098, 2024). "In this study, we examined the potential involvement of YARS1 in bladder cancer using differential analysis." (PMID 38506098, 2024). "The results of this analysis provided additional support for the substantial role of YARS1 in determining the prognosis of bladder cancer." (PMID 38506098, 2024). "Both KEGG and GSEA findings confirmed a robust connection between YARS1 and the immune microenvironment of bladder cancer." (PMID 38506098, 2024). "Our findings indicated a positive correlation between high YARS1 expression and increased stemness scores in bladder cancer samples." (PMID 38506098, 2024). "Subsequently, we performed functional enrichment analysis of these differentially expressed genes to validate the potential role of YARS1 in bladder cancer." (PMID 38506098, 2024). "Based on these findings, we conclude that YARS1 holds promise as a valuable prognostic biomarker for patients diagnosed with bladder cancer." (PMID 38506098, 2024). "Our findings revealed a noteworthy correlation between YARS1 and immune infiltration in bladder cancer, as determined using the XCELL algorithm and single‐cell analysis." (PMID 38506098, 2024). "Finally, we explored the correlation between these methylation probes and YARS1 expression in bladder cancer." (PMID 38506098, 2024). "Interestingly, our analysis revealed a significant correlation between YARS1 and 21 genes that co‐regulate ferroptosis and cellular senescence in bladder cancer samples." (PMID 38506098, 2024). "Gene enrichment analyses revealed that YARS1 may play a role in regulating the senescence, ferroptosis and stemness pathways in bladder cancer cells." (PMID 38506098, 2024). "However, there is currently a dearth of research exploring the biological function of YARS1 in bladder cancer and its potential as a therapeutic target." (PMID 38506098, 2024).
bladder cancer (continued). "Finally, we established a ceRNA network that is directly linked to the overall prognosis, YARS1 can serve as a prognostic biomarker for bladder cancer; its interaction with MYC has implications for bladder cancer cell senescence, ferroptosis and stemness." (PMID 38506098, 2024). "This validates the potential use of YARS1 as a predictive biomarker for bladder cancer." (PMID 38506098, 2024). "The differential expression of YARS1 in bladder cancer is substantiated in this study." (PMID 38506098, 2024). "Finally, in addition to our investigation of YARS1, we explored its correlation with immune cells in bladder cancer." (PMID 38506098, 2024). "Hence, we compared the expression of YARS1 in high‐ and low‐grade bladder cancers, and our results demonstrated a significant increase in YARS1 expression in high‐grade bladder cancer." (PMID 38506098, 2024). "Moreover, within paired samples, YARS1 expression was significantly higher in bladder cancer tissues than in normal bladder tissues." (PMID 38506098, 2024). "Furthermore, multivariate COX regression analysis results indicated that YARS1 has the potential to serve as a prognostic biomarker in patients with bladder cancer." (PMID 38506098, 2024). "Based on these findings, we hypothesized that YARS1 interacts with MYC to regulate bladder cancer cell senescence, ferroptosis and stemness." (PMID 38506098, 2024). "In conclusion, we analysed the correlation between YARS1 and different methylation probes in bladder cancer, and suggest that YARS1 may play an oncogenic role in bladder cancer through these methylation probes." (PMID 38506098, 2024). "Additionally, we investigated the potential role of YARS1 in bladder cancer using gene enrichment analyses." (PMID 38506098, 2024). "Overall, our results suggest that YARS1 could serve as a valuable prognostic biomarker for bladder cancer and may have a significant impact on various biological functions of bladder cancer cells." (PMID 38506098, 2024). "Furthermore, an assessment was conducted to ascertain the prognostic significance of YARS1 in bladder cancer, and the results demonstrated that patients with heightened YARS1 expression had an unfavourable prognosis." (PMID 38506098, 2024). "Our findings revealed that YARS1 interacts with the well‐known oncogene MYC, and together they play crucial roles in regulating ferroptosis, senescence and stemness in bladder cancer cells." (PMID 38506098, 2024). "The results indicated a substantial increase in YARS1 expression in bladder cancer tissues compared to that in normal bladder tissues." (PMID 38506098, 2024). "Furthermore, our investigations revealed an intricate interaction between YARS1 and MYC in the regulation of bladder cancer cell senescence, ferroptosis and stemness." (PMID 38506098, 2024). "Previous research has demonstrated the prognostic value of CD8+ T cells, and this study identified a regulatory effect of YARS1 on CD8+ T cells, suggesting that YARS1 may affect the prognosis of patients with bladder cancer by influencing CD8+ T cells." (PMID 38506098, 2024).
hepatocellular carcinoma (1 paper, 2024). A malignant tumor that arises from hepatocytes. "In the diagnosis of hepatocellular carcinoma, YARS1 exhibits clinical significance and enhances cancer progression by activating the PI3K/AKT signalling pathway." (PMID 38506098, 2024).
pancreatic disease (1 paper, 2023). "Pathogenic variants in YARS1 gene have been recently associated with infantile-onset multisystem neurologic, endocrine, and pancreatic disease." (PMID 37784170, 2023).
cancer (10 papers, 2020 to 2025). A tumor composed of atypical neoplastic, often pleomorphic cells that invade other tissues. "Additionally, the presence of functional clusters, such as the interactions among KPNA2, DHX37, and YARS1, indicates possible shared roles in critical cellular processes like RNA processing, which are often implicated in cancer progression." (PMID 39330100, 2024).
neurodevelopmental disorder (2 papers, 2021 to 2023). A behavioral and cognitive disorder with onset during the developmental period that involves impaired or aberrant development of intellectual, motor, or social functions. "The diverse clinical spectrum of ARS1-associated disorders is related to mutations affecting the various non-canonical domains of ARS1, and impaired protein translation is likely not the exclusive disease-causing mechanism of YARS1- and ARS1-associated neurodevelopmental disorders." (PMID 34536092, 2021).
autosomal recessive disease (1 paper, 2021). Autosomal recessive form of disease. "First, the hypothesis of impaired protein synthesis lacks to explain the considerable clinical variability of autosomal recessive diseases associated with YARS1 and also other ARS1-deficiencies." (PMID 34536092, 2021).
YARS1 also shares sentences with these, for which no sentence is quoted: tumor (8 papers); neuropathy (4); peripheral neuropathy (3); breast carcinoma (2); distal motor neuropathy (2); liver disease (2); polyneuropathies (2); Ataxia (1); autism (1); Charcot Marie Tooth type 2 (1); colon cancer (1); deafness dystonia syndrome (1); developmental delay (1); distal hereditary motor neuropathy (1); Failure to thrive (1); frontotemporal lobar degeneration (1); Hearing impairment (1); hypothyroidism (1); lung carcinoma (1); malaria (1); melanoma (1); microcytic anemia (1); Primary amenorrhea (1); primordial dwarfism (1); respiratory disease (1); schizophrenia (1); spastic hemiplegia (1); steatosis (1); tuberculosis (1); viruses infections (1).